MMP9 (matrix metallopeptidase 9)
Diseases named in the same sentence as MMP9 in open-access papers (continued):
Sharing a sentence is not in itself a finding about the gene and the disease.
tumor (continued). "Molecular analysis revealed that IL-23 could upregulate MMP9 expression via NF-κB/p65 signaling activation and IL-17A could improve IL-23 expression in tumor cells directly via activating NF-κB/p65 signaling pathway." (PMID 23050001, 2012). "Therefore, the virus-mediated over-expression of MMP-9 enhances virotherapy of the primary tumor while sustaining the rVACV-metastasis reducing effect." (PMID 22917220, 2012). "Expression of mRNA for Lcn2, Mmp9, Bdh2, 24p3R, megalin (another receptor mediating cellular uptake of lipocalin-2), and transferrin receptor (Tfrc) were determined in each tumor and reported as mean of all tumors/tissue samples in each of the four groups of mice." (PMID 22737251, 2012). "MMP2 and MMP9, otherwise known as gelatinases, are strongly upregulated in cancers of the lung, colon, breast, skin, and prostate, which are correlated with enhanced tumor invasiveness and metastasis." (PMID 23031673, 2012). "Furthermore, along with unmethylated MMP-9, this tumour showed increased transcription of MMP-9 when compared to the control group." (PMID 22866959, 2012). "Also we found that active MMP2 was present at all stages of tumor while active MMP9 just at more advanced tumors." (PMID 23304126, 2012). "The intra-tumoral MMP-9 content was quantified by immunohistochemistry in tumor sections." (PMID 22917220, 2012). "Moreover, we found that at identical concentrations CA decreases the activity of important ECM-degrading proteases, as uPA, MMP-9 and MMP-2 which are closely associated with tumor progression." (PMID 22246562, 2012). "Vegfr1 TK knockout: Impaired tumor metastasis by suppression of MMP-9 expression." (PMID 24213317, 2012). "As MMP-9 can also induce angiogenesis by increasing the bioavailability of VEGF which may stimulate primary tumor growth, we quantified the BVD in sections of tumors from infected and uninfected mice." (PMID 22917220, 2012). "On the other hand, tumor size and node metastasis were significantly associated with MMP-9 expression at negative margins (p-value: Tumor Size=0.002; Node Metastasis=0.043)." (PMID 22410369, 2012). "The over-expression of MMP-9 co-localized with GFP-positive GLV-1h255-infected tumor areas." (PMID 22917220, 2012). "This may provide an explanation for unexpected, inverse correlation between MMP-9 expression and tumor promotion." (PMID 22701711, 2012). "Pre-ALP was also positively correlated with MMP-9 expression (p = 0.015) in tumor tissue." (PMID 22333159, 2012). "Moreover, AP-1 and NF-kappaB transcription factors can induce expression and activation of MMP-9 by interacting with these binding sites, and consequently promote tumor progression." (PMID 22967049, 2012). "We determined the vascular density in PC-3 tumor sections at 7 days p.i. to elucidate whether it is influenced by the GLV-1h255 mediated over-expression of MMP-9." (PMID 22917220, 2012). "Metalloproteinases are essential for tumor promotion, progression, and invasion and AP-1 and NF-κB play a dominant role in the transcriptional activation of the majority of MMPs including MMP-9 and MMP-2." (PMID 22776414, 2012). "Yet those carcinomas that do arise in the absence of MMP-9 show a greater loss of keratinocyte differentiation, indicative of a more aggressive and higher grade tumour." (PMID 23905066, 2012). "Tumor-associated macrophages play an important role in tumor progression due to production of several angiogenic factors, such as VEGF, IL-8, inflammatory cytokines (IL-1 and IL-10) and proteases (MMP-2 and MMP-9)." (PMID 23024650, 2012). "Assessed tumor cell characteristics including secretion of matrix metalloproteinase-9 (MMP-9), invasion, and colony formation were fortified by evaluating expression of relevant genes by real-time reverse transcription polymerase chain reaction and by Western blot." (PMID 22626610, 2012). "Our study also showed that expression of MMP-2 and MMP-9 are differentiated among tumours." (PMID 23107277, 2012).
tumor (continued). "As known, MMP-9 expression and function is involved during lung metastasis of tumor, so we concerned whether serum ALP was connected with MMP-9 expression." (PMID 22333159, 2012). "First, HPV-transformed cells can influence MMP-9 expression by tumor infiltrating myeloid cells." (PMID 22438955, 2012). "The production of cytokines such as IL-8 and MMP-9 was increased, which could further help inducing angiogenesis and modifying the extracellular matrix in the tumor microenvironment." (PMID 22195048, 2011). "The findings indicate that the cytoplasmic domain of CD248 participates in the suppression of SM22α expression, providing a mechanism to help explain reduced stromal cell activation, migration and MMP-9 release and thus, less tumor expansion in the CD248CyD/CyD mice." (PMID 21549007, 2011). "MMPs may be divided into subgroups, one comprised of type IV collagenases (gelatinases) such as MMP-2 and MMP-9, which play major roles in tumor growth, angiogenesis, and metastatic disease." (PMID 21490745, 2011). "Conversely, others have shown that the ectodomain of CD248 does interact with components of the ECM, including collagen, fibronectin and Mac-2 BP/90 K, and also participates in promoting tumor growth by modulating cellular adhesion and migration and promoting the release of MMP-9." (PMID 21549007, 2011). "NF-kappaB exerts its metastasis-promoting effect by regulating the transcription of a subset of genes known to be important for tumor metastasis, such as prometastatic matrix metalloproteinase 9 (MMP9), a urokinase-like plasminogen activator (uPA), which is MMP9 activator, and heparanase." (PMID 24213137, 2011). "It is reported that cathepsin G is up regulated through tumor stromal interactions and activates Pro-MMP9, active MMP9 cleaves and releases active TGF-beta, and active TGF-beta can then promote tumor growth and enhance osteoclast activation and subsequent bone resorption." (PMID 21859454, 2011). "Importantly, these studies provide evidence that targeting the production of MMP-9 within the tumour microenvironment is a successful alternative to trying to inhibit MMP-9 itself that has failed or resulted in toxicity." (PMID 22005011, 2011). "In addition to its role in the initiation and development of ATL, deregulated NF-κB induces expression of many genes involved in tumor progression and metastasis such as matrix metalloproteinase-9 (MMP-9)." (PMID 21743832, 2011). "On the transcriptional level, livers from tumor-bearing mice exhibited significant up-regulation of Myc, Jun, Mmp9, and Vegfa that might contribute to an increased incidence of tumorigenesis." (PMID 21725989, 2011). "CD11b+ cells in the irradiated tumour may also help recruit ECs into the tumour or help reorganise the tumour extracellular matrix via MMP-9 to mediate revascularisation." (PMID 21587260, 2011). "The relationship between CCR7 and MMP-9 suggests that these two factors may enhance each other and promote tumor dissemination synergistically." (PMID 21548969, 2011). "Down-regulation of MTA1 by RNAi approach led to re-expression of ER alpha in ER-negative breast cancer cell lines MDA-MB-231, and reduced protein levels of MMP-9 and CyclinD1, as well as decreased tumor cell invasion and proliferation, more cells were blocked in G0/G1 stage(P < 0.05)." (PMID 21595884, 2011). "Furthermore, TG2 induced the PI3K/Akt activation and GSK3β inactivation in A431 tumor cells and this increased Snail and MMP-9 expression resulting in higher cell motility." (PMID 21777419, 2011). "Tumor cell derived MMP-2 or MMP-9 were reported to elicit secretion of soluble VEGF from the ECM." (PMID 22267953, 2011). "Inhibition of phosphorylated Erk1/2 and Akt and c-Junexpression by RRIG1 may mediate RRIG1 suppression of cell growth, while reduced MMP9 expression by RRIG1 mediates the reduced tumor cell mobility and invasion capacity." (PMID 21266059, 2011).
tumor (continued). "Consistent with this hypothesis, deletion of MMP9 in a mouse model of pancreatic β-cell carcinoma, Rip1Tag2, suppressed tumor progression." (PMID 21349159, 2011). "On the other hand, MMP-9, one of the two types IV collagenases, was extensively studied in human cancer, and a large body of evidence indicates its expression correlates well with tumor invasion and metastasis." (PMID 21760774, 2011). "The limited presence of the active form of MMP-9 may indicate a minor role for this gelatinase within the tumor, and it appears to be of little prognostic or pathogenetic value, as observed in canine tumors." (PMID 21726449, 2011). "Conversely, others have reported that TSP-1 increases MMP-9 activity and tumor cell invasion, suggesting that the interaction between matricellular proteins may be context specific." (PMID 20671917, 2010). "In addition, in residual tumour samples, the amount of MMP-9 mRNA seemed to be reduced at the end of RGZ treatment compared with that in the control group, whereas an opposite trend was observed for TIMP-1 expression." (PMID 20068562, 2010). "One mechanism of the pro-tumor role of galectin-7 may involve induction of MMP-9, which plays an important role in cancer progression and metastasis." (PMID 20546628, 2010). "MMP-9 plays an important role in tumour invasion and metastasis by degrading ECM components." (PMID 20152059, 2010). "In addition, western blot analysis of VEGF expression indicated that VEGF levels in MMP-9-induced Daoy-EV cells are almost two-fold higher than that of parental control cells, which probably contributed to the enhanced tumour growth induced by these cells." (PMID 20087345, 2010). "Recent observations pointing to a potential mechanism for the progression of ovarian, nasopharyngeal and pancreatic cancers indicate that catecholamine may modulate the expression of matrix metalloproteinase (MMP)-2 and MMP-9 by stroma and tumor cells." (PMID 20939893, 2010). "Modulation of its mRNA stability might be important during malignant conversion and metastasis, when tumor cells need to induce or maintain MMP-9 levels in response to changing environmental cues." (PMID 20942921, 2010). "MMP-2 and MMP-9 expression were correlated with the tumor EI, EP and the maximum diameters." (PMID 23554622, 2010). "We also show that this inhibition of tumour growth could be mediated in part by inhibition of MMP-9." (PMID 20087345, 2010). "Studies have also demonstrated that NF-κB could regulate several proteins that promote tumor growth, invasion and metastasis, such as urokinase-type plasminogen activator and MMP9." (PMID 20716363, 2010). "Overexpressed MMP9 in NPC may accelerate tumor growth by inducing angiogenesis and enhance local cell invasion and metastasis by degrading the extracellular matrix." (PMID 20534121, 2010). "One explanation is that these findings could be due to the link that both MMP-2 and MMP-9 have with apoptosis, which is known to commonly occur with Dz13 treatment of tumour cells." (PMID 20334687, 2010). "During this process, degradation of the extracellular matrix and components of the basement membrane by proteases, such as matrix metalloproteinase (MMP)-2, MMP-9, and urokinase plasminogen activator (uPA), plays a critical role in tumor invasion and metastasis." (PMID 20429953, 2010). "In particular, MMP-2 and MMP-9 were reported to correlate with tumour grade and metastasis." (PMID 20587068, 2010). "Nevertheless, a high expression of pro-MMP9 was observed in EDP-treated tumours lysates." (PMID 20959825, 2010). "In vivo colonic cell studies suggest AP-2 up-regulates the over-expression of the cell adhesion molecule E-cadherin needed for cell cohesion, while simultaneously decreasing transcription of the matrix metalloproteinase (MMP)-9 involved in migration of tumour cells through adjacent stromal tissue." (PMID 20025767, 2009).
tumor (continued). "Since MMP-9 is implicated in both early and late processes of tumor progression through the degradation of the extracellular matrix and basement membranes, the question whether NGAL and MMP-9/NGAL complex contributes to tumor progression was raised." (PMID 19889214, 2009). "Tumour-associated macrophages are known to contain many proangiogenic factors, such as VEGF, TNF-α, CXCL-8, bFGF and proteases such as MMP-2 and MMP-9." (PMID 19352388, 2009). "We assessed the ability of chronic, low-level cadmium to induce transformation in the MCF-10A ER-negative human breast epithelial cell line using various measurements including MMP-9, an enzyme secreted to degrade the extracellular matrix and facilitate tumor cell invasion." (PMID 20049202, 2009). "Furthermore, the samples derived from tumors showed a higher MMP-9 expression tendency than the adjacent non-tumor tissue specimens." (PMID 19144199, 2009). "MMP-9 knockout mice were used to demonstrate a role for Gr+/CD11b+ cells in tumor vascularization." (PMID 19545375, 2009). "Indeed,some of the most prominent tumor-promoting mediators of macrophages—TNFα, MMP9, iNOS—are known to be repressed by PPARγ ligation." (PMID 18615187, 2008). "Furthermore, MMP-9 can induce VEGF to be secreted into ECM resulting in enhanced tumor angiogenesis." (PMID 18983651, 2008). "Perhaps increasing MMP-9 activity portends tumor progression and it could be used as a marker to detect early tumor progression." (PMID 18186943, 2008). "Similarly, the NF-κB target gene MMP9 is important for skin carcinogenesis and isexclusively produced by inflammatory cells." (PMID 18615187, 2008). "Another source of this MMP-9 may be from bone marrow-derived hematopoietic progenitor cells helping tumor angiogenesis." (PMID 18186943, 2008). "VEGF, NF-κB, PCNA, MMP-2 and MMP-9 expression in tumor tissue was also assessed." (PMID 18983651, 2008). "Multivariate analysis against the prognosis-associated parameters gender, age and TNM classification showed that the MMP-2 SNP was independently associated with survival, whereas the tumour protein levels of MMP-2 just lost and MMP-9 completely lost their significance." (PMID 18506186, 2008). "Low MMP-9 expression in the tumour, leading to insufficient production of antiangiogenic factors, could also contribute to the worse prognosis of these patients." (PMID 18506186, 2008). "Furthermore, we studied the effects of RGZ on tumor cell viability, adhesion, migration and levels of MMP-9 and NO production." (PMID 18261208, 2008). "Moreover, stromal MMP9 contributes to the malignant behavior of cancer cells by promoting new vessel sprouting and tumor growth through enhanced expression of VEGF." (PMID 17567918, 2007). "Some recent studies suggest that tissue inhibitor of metalloproteinases-1 (TIMP-1) and gelatinase B (MMP-9) could be utilized as novel tumor markers in the determination of prognosis in the carcinomas of head and neck, breast, ovary, and colon." (PMID 19662197, 2007). "High MMP-9 expression correlates significantly with tumoural aggressiveness and poor prognosis." (PMID 17848954, 2007). "However, despite the potential influence of host MMPs, the tumor volume was still reduced in both experimental groups, suggesting that fibroblast derived MMP-2 and MMP-9 promote tumor cell growth in vivo." (PMID 16515711, 2006). "However, it is well known that, for example, the ratios of active to total MMP2 and MMP9, respectively are changed in tumour tissue and also in plasma." (PMID 16901349, 2006). "However, MMP-2 null and MMP-9 null fibroblasts combined with FaDu tumor cells formed significantly larger tumors than FaDu cells injected alone (p = 0.04 and 0.009, respectively)." (PMID 16515711, 2006). "MMP-9 may have a role in the destruction of the extracellular matrix of the tumour overall, not only at the invasive front." (PMID 14647147, 2003). "MMP-9 expression in tumours was reported in gastric, colon, pancreatic, and cervical cancers." (PMID 14647147, 2003).
tumor (continued). "Tumours with MM and SM invasion had significantly more MMP-9 expression (P=0.004)." (PMID 14647147, 2003). "sCD44 can disrupt CD44/MMP-9 clusters and inhibit tumor metastasis in vivo." (PMID 19570245, 2002). "Explicit differences between MMP-2 and MMP-9, with respect to both levels of active enzyme and correlations with clinicopathological parameters, strongly suggest different roles for the gelatinases in tumour progression." (PMID 12085179, 2002). "If so, early or slowly invading and growing tumours may trigger more explicit effects of this host defence mechanism, in this case production of MMP-9, than fast and diffuse invading tumours." (PMID 12085179, 2002). "Still, it remains to be established if MMP-9 plays a significant role in tumour progression in CRC." (PMID 12085179, 2002). "However, expression of MMP-9 was significantly reduced in tumor cells (p < 0.05 for both doses)." (PMID 41009634, 2025). "This, together with the lack of significant associations with tumor stage or survival, suggests that serum MMP9 may reflect systemic processes rather than tumor-specific aggressiveness." (PMID 41041068, 2025). "Furthermore, candidalysin activates matrix metalloproteinases (MMPs), especially MMP-9, facilitating tumor invasion, angiogenesis, and metastasis by degrading the extracellular matrix and stimulating angiogenic factors such as vascular endothelial growth factor (VEGF)." (PMID 41322070, 2025). "Besides VEGF, Matrix metalloproteinase 9 (MMP9) is a tumor angiogenic factor." (PMID 41326479, 2025). "Additionally, these drugs exhibit antiproliferative effects involving cell cycle regulators, lysosomal enzymes, or growth factors (e.g., matrix metallopeptidase 9 and vascular endothelial growth factor), which are known to participate in tumor growth and metastasis." (PMID 40943762, 2025). "Importantly, silk sericin-containing PBR could respond to the local intracellular environment in the tumor with acidic pH and overexpressed MMP-9, collapsing into Bi, Se, and scattered Pt nanoparticles (NPs) and finally be cleared from the body." (PMID 40083934, 2025). "However, under hypoxic conditions, the expression dynamics of TIMP1 exhibit a dual nature: it restricts tumor invasion by inhibiting MMP-9 and reducing extracellular matrix degradation, but simultaneously promotes chemoresistance by activating the integrin β1/FAK signaling pathway." (PMID 41189944, 2025). "For example, MMP9+ TAMs may play a role in tumor tissue remodeling, CX3CR1+ TAMs may exhibit unique phagocytic patterns, ECM-associated TAMs (ECMMac) involved in extracellular matrix remodeling are upregulated, and SPP1AREGMac exhibit distinct distribution within tumor tissues." (PMID 40191203, 2025). "Finally, it was also found that the circDENND4C/miR-200b/MMP-9 regulatory axis might be involved with cell adhesion and tight junction to influence tumor metastasis." (PMID 40034591, 2025). "Importantly, our study extends this understanding by highlighting the modulation of key biochemical markers, including VEGF, matrix metalloproteinase-9 (MMP9), stromal cell-derived factor-1α (SDF-1α), and carcinoembryonic antigen (CEA), which are closely linked to tumor progression and angiogenesis." (PMID 40821654, 2025). "In fact, MMP‐9 plays a key role in the metastatic process by enhancing the tumor seeding and growth properties of the metastatic bone niche through extracellular matrix degradation, osteoclast activation, and by down‐regulating tumor‐infiltrating cytotoxic T lymphocytes and natural killer cells." (PMID 40304052, 2025). "Importantly, sera MMP-9 levels can be monitored over time non-invasively, and an increase might indicate tumor progression." (PMID 41573658, 2025). "Several CAF IHC biomarkers, particularly CD163, MMP-9, periostin, and vimentin, significantly associated with prognosis in CRC, could be proposed as surrogates for the phenotypical characterization of the tumor microenvironment." (PMID 41450913, 2025).